CTSL (cathepsin L)
Diseases named in the same sentence as CTSL in open-access papers (continued):
Sharing a sentence is not in itself a finding about the gene and the disease.
cancer (continued). "In cancer cells, nuclear p-STAT3-S705 can regulate the transcription of several autophagy-related genes such as BCL2 family members (e.g., BECN1, PIK3C3, CTSB, CTSL, PIK3R1, HIF1A, and BNIP3) and microRNAs with targets of autophagy modulators." (PMID 32565533, 2019). "Compared with the diploid, other types (deep deletion and shallow deletion gain amplification) of CNV were significantly correlated with gene expressions of DDX56, ZC3H12D, and PSMC5 (p < 0.05), except for CTSL (p > 0.05), indicating that CNV might regulate the expression of these genes in cancer." (PMID 35647031, 2022). "Notably, in some cell lines (MDA-MB-231, U2-OS, and PC-3) cathepsin B, but not cathepsin L, was found bound to the membrane, which support their different functions in cancer." (PMID 31803426, 2019). "However, we observed cathepsin L positivity in the photoreceptor layers of control tissues, indicating its lysosomal functions in the retina tissues, unlike its metastatic potential in cancers." (PMID 36291907, 2022). "While the role of CTSD and CTSL has not been specifically demonstrated in HCC, CTSD has been shown to be directly involved in invasion and metastasis in various other cancer types, including breast cancer." (PMID 36289617, 2022). "For CTSL and CTSD, there is no direct evidence available for the effect of genetic variations in HCC or cancer in general." (PMID 36289617, 2022). "Likewise, establishing how CP1/CTSL facilitates ASP invasion, characterizing the signal released by MMP2 to laterally inhibit tip cell fate, and determining how proteolytic enzymes cooperate during ASP development might provide new insights regarding ECM remodeling in human cancer progression." (PMID 30018198, 2018). "Unlike other receptors, such as ACE2, TMPRSS4, and CTSL, increased ISG20 expression may prevent viral invasion in these types of cancer." (PMID 36177004, 2022).
infection (121 papers, 2009 to 2025). The state of being infected such as from the introduction of a foreign agent such as serum, vaccine, antigenic substance or organism. "We confirmed that CTSL cleavage is essential during infection of all emerged SARS-CoV-2 variants (including the recently emerged Omicron variant) by pseudovirus (PsV) infection experiment." (PMID 35668062, 2022). "Similar findings were reported for porcine reproductive and respiratory syndrome virus (PRRSV) whose infection causes upregulation of cathepsin L and heparanase, leading to a decrease of cell surface HS chains and, in turn, promoting viral release." (PMID 36012353, 2022). "Whereas NT cells succumbed to VSV-EBO GP (GFP) infection within 26 h, the viability of CTSL- and WDR81-deficient cells was unaffected." (PMID 35320319, 2022). "The results of the experiments presented showed that CTSL activity is increased in alveolar septum, alveoli, tracheas and lungs in association with the inflammatory response after infection, as has been found in mice infected with Pseudomonas aeruginosa." (PMID 30986254, 2019). "Previous studies have shown that cystatin C and cathepsin L are involved in the rapid responses of both aquatic and terrestrial animals to various stimuli, including lipopolysaccharide (LPS), pathogenic bacteria, and virulent infection." (PMID 40282805, 2025). "Analysis of a panel of host cysteine proteases in vivo demonstrated that E64 decreased the activation of cathepsin L; subsequently, we found that the infection of cathepsin L-deficient mice yielded lower catheter and bladder colonization compared to wild-type mice." (PMID 40980878, 2025). "However, after the CTSL cleavage sites were mutated to glycine in CS mutant, these PsVs gradually lost most of their infection ability in all four cell lines." (PMID 35668062, 2022). "In contrast, upregulation of the cathepsin L and Z-like cysteine proteases may have roles in host immune evasion in genotype 0 infections, which are associated with low proliferation, low inflammation and non-destructive development." (PMID 35071050, 2021). "This was supported with immunoblots using antibodies against cathepsin L, X and S, confirming that these proteases show increased or unchanged expression during infection." (PMID 40274809, 2025). "Cathepsin L and cystatin B co-localize within viral replication centers from early infection, and siRNA-mediated knockdown of these cathepsins before infection enhances viral yields, indicating that ECTV manipulates cathepsins to optimize replication." (PMID 41369389, 2025). "The results showed that CTSL overexpression partially rescued pseudovirion infection, particularly at low concentrations of UNC0638 (0.25 μM and 1 μM)." (PMID 40530850, 2025). "Infection with neHEV was significantly blocked with the treatment of pan-cathepsin inhibitor K11777, cathepsin L inhibitor CAA0225, and cathepsins B and L inhibitor E64d." (PMID 40135892, 2025). "This study reveals the infection mechanisms of PDCoV in human-derived cells, highlighting the roles of CTSL, TMPRSS11E, and furin in viral entry and release." (PMID 40787987, 2025). "CtsL inhibitors significantly reduce infection and represent a promising therapeutic approach for COVID-19 patients." (PMID 41369389, 2025). "This is consistent with the presence of CTSL in the midgut, as observed in some other insects, such as Acyrthosiphon pisum, where CTSL plays a crucial role in food digestion and regulating immune responses during infection." (PMID 38451906, 2024). "The ACE2 enzyme is stimulated by the transepithelial serine protease type II TMPRSS2 or cathepsin L. Additional receptors involved in the infection process have also been described thus far: CD147/EMMPRIN/Basigin, Axl and Neuropilin-1 (NRP1)." (PMID 38592169, 2024). "CTSL in the hepatopancreas of Litopenaeus vannamei (Boone) was downregulated after infection with WSSV." (PMID 36896191, 2023).
infection (continued). "P. dicentrarchi secrete proteases, most predominantly cysteine proteases of the cathepsin L, B and D protease subfamilies, which mediate host entry, the spread of the infection, and the disruption or modification of the function of immune cells and molecules." (PMID 37508344, 2023). "K777 is also demonstrated to inhibit CTSL in vitro and to block the infection of SARS-CoV-2 in various cell lines." (PMID 38033388, 2023). "Accordingly, out of the seven known human CoVs, only SARS-CoV and SARS-CoV-2 have conserved CTSL cleavage sites at T259 and Y636, indicating that CTSL cleavage is crucial for the infection process of SARS-CoV/SARS-CoV-2 and life cycle." (PMID 38033388, 2023). "Cathepsin L also plays a role in antigen processing, suggesting that only the non-permissive mice are able to process exogenous proteins effectively during infection prior to the activation of CD4 + T cells." (PMID 36883013, 2023). "Previous studies have suggested that TMPRSS2 and CTSL/CTSB inhibitors effectively prevent the infection of other coronaviruses, including SARS-CoV, MERS-CoV, and human coronavirus (HCoV)-229E58–60." (PMID 37990007, 2023). "Correspondingly, overexpression of Cathepsin L enhanced pseudovirus infection in human cells, and knockdown in vitro and application of Cathepsin L inhibitor drugs prevented infection both in vitro and in vivo." (PMID 37193304, 2023). "For WT PsV, overexpression of the CTSL gene markedly increased its infection efficiency, while knockdown of this gene significantly reduced the infection efficiency, similar to our previous finding." (PMID 35668062, 2022). "By contrast, stimulation of the bradykinin-receptor B2 (BDKRB2) is decreased due to the inhibition of cathepsin L, a kininogenase involved in bradykinin production and present at the infection site." (PMID 36143272, 2022). "The treatment with teicoplanin suppressed the proteolytic activity of CTSL on spike and prevented the cellular infection of different pseudotyped SARS-CoV-2 viruses." (PMID 35572668, 2022). "In the absence of TMPRSS2, however, SARS-CoV-2 enters cells by ACE2-mediated endocytosis, undergoes proteolytic activation by cathepsin L in low-pH-containing endosomes, and fuses its membrane with a limiting endosomal membrane for infection." (PMID 34705560, 2022). "Under this experimental setting the infection’s endosomal route is eliminated and indeed the fusion is refractory to the cathepsin L inhibitor." (PMID 35388061, 2022). "Further supporting a requirement for endocytosis, the knockdown of cathepsin L (CTSL) also inhibited infection." (PMID 36314791, 2022). "As expected, we found that the CTSL-specific inhibitors can nearly completely prevent infection of SARS-CoV-2 variant PsVs and reduce infection of live SARS-CoV-2 by 103–104-fold in Vero E6 cells." (PMID 35668062, 2022). "Several CRIPSR-mediated knock-out and animal infection experiments have highlighted the importance of CTSL in SARS-CoV-2 infection." (PMID 35572668, 2022). "Based on all these findings, we believe that the endosomal proteinase CTSL plays vital roles in the infection of SARS-CoV, MERS-CoV, SARS-CoV-2, and possibly other coronaviruses." (PMID 35572668, 2022). "In the context of infection, CTSL cleaves the SARS-CoV-2 S protein and enhances entry into host cells, an effect that was strongly inhibited by CTSL inhibitors." (PMID 35053020, 2021). "In hBMEC and THP1 cells, the colocalization of MCVs with cathepsin L was significantly decreased during M. tuberculosis H37Ra infection, while it was significantly increased during M. tuberculosis H37Rv infection over time." (PMID 34402643, 2021). "Among these, different isoforms of cathepsin L and B, peroxiredoxin, calmodulin, or glutathione S-transferase were recognized from the beginning to the end of the experimental infection, suggesting their potential role as immunomodulatory antigens." (PMID 34207550, 2021).
infection (continued). "As soon as the cathepsin-L-dependent endocytic pathway of infection (via ACE2 receptor) is participating, the effectiveness of TMPRSS2 inhibitors decreases rapidly." (PMID 32668803, 2020). "If the lysosomal pH increases, cathepsin L activity diminishes, thereby decreasing the rate of cleavage, fusion, and infection." (PMID 32668803, 2020). "CTSL activity is required for infection by several viruses like SARS and MERS that enter cells via the endosomal route." (PMID 33312949, 2020). "The inhibitor blocked SARS-CoV (IC50 = 273 ± 49 nM) and Ebola virus (IC50 = 193 ± 39 nM) entry into the human embryonic kidney (HEK) 293T cells, a process that utilizes cathepsin L-mediated proteolysis for host cell infection." (PMID 32041276, 2020). "First, the lent‐CTSL infection led to the enhancement of the CTSL in both the WT and HO corneal fibroblasts (lanes 2, 4, 6, 8 and 10)." (PMID 32667742, 2020). "Cathepsins and neutrophils both contribute to the presence of secretory granules during infection, however CTSL can also break down lung elastin that can also lead to tissue damage." (PMID 33187194, 2020). "The expression of LEP and CTSB remained unchanged at 6 h post-infection, whereas CTSL showed down-regulation, which is in agreement with earlier reports." (PMID 32275661, 2020). "Close examination of cellular protein distribution showed that beginning from early stages of infection, the remnants of cathepsin L and cystatin B co-localized and partially co-localized with viral replication centers (viral factories), respectively." (PMID 31077130, 2019). "Cathepsin L is involved in antigen presentation in the early events of the immunological response to infection." (PMID 30873029, 2019). "Previous reports suggested that CTSL, by cleaving pathogen-associated proteins, helps Ebola, Hendra and SARS viruses to enter cells, thereby advancing infection." (PMID 27716790, 2016). "Vaccination of sheep and cattle with purified F. hepatica cathepsin L elicits protection (50–73%) and anti-fecundity effects against challenge infection." (PMID 26799066, 2016). "For example, RNAi-mediated knockdown of cathepsin L and B expression has been shown to prevent NEJs from crossing the intestine and vaccine trials with cathepsin L1 have provided partial protection against infection and pathology." (PMID 25887684, 2015). "Both serpins have been shown to inhibit the cysteine protease cathepsin L, which is normally highly expressed in lysosomes and, indeed, in M. hominis-infected HeLa cells, cathepsin L2 is downregulated 48 h post infection." (PMID 23326599, 2013). "Overall, our results indicate an intracellular pathway of C3 activation that in T cells is catalyzed by CTSL and occupies a central niche in basal cellular homeostasis and in immunological T cell effector function during infection." (PMID 24315997, 2013). "HPV16 reporter-virions were treated with cathepsin B or cathepsin L protease for various amounts of time at 37°C, added to cells, and infections were analyzed by flow cytometry after 48 hours (for DsRED expression)." (PMID 19619315, 2009). "MEFs deficient for either cathepsin B, cathepsin L, or wild type MEFs, i.e., cathepsin B and L positive, were infected with HPV16 reporter-virions and analyzed for infection levels after 48 hours." (PMID 19619315, 2009). "Cell-surface hACE2 co-internalized with SARS-CoV-2 in endosomes may thus promote infection by changing S conformation, allowing endosomal cathepsin L to cleave S." (PMID 40964294, 2025). "These discoveries suggest that proteases in the supernatants may mainly contribute to the initial viral entry, whereas the subsequent viral replication and productive infection require the involvement of intracellular proteases, such as CTSL and/or furin." (PMID 40787987, 2025). "In contrast, kidney colonization may reflect downstream effects of ascending infection and anatomical variation and thus be less directly influenced by CTSL activity." (PMID 40980878, 2025).
infection (continued). "Upon infection, M. bejeranoi deploys an array of activated proteases, including cathepsin D and cathepsin L, which may act to degrade hemoglobin, as in other parasites." (PMID 38891869, 2024). "Another plausible explanation lies in the concentration range of PI fractions used during and after infection of the Vero E6 cell line: the concentration of cathepsin L inhibitors — selected following the cell viability tests — was too low to neutralize cathepsin L protease activity." (PMID 38381158, 2024). "Among the proteins downregulated by infection and recovered by Ago1-knockdown, Cathepsin L (CTSL) has been shown to play a crucial role for a Th1-type immune response during L. major infection by processing of soluble Leishmania antigen (SLA) for presentation on MHC class II molecules." (PMID 38098491, 2023). "The naturally derived reoviruses uncoated less efficiently in L929 cells and were more dependent on extracellular proteolysis for productive infection compared to lab-adapted strains, which depend mainly on lysosomal cathepsin L for intracellular uncoating with a minor contribution by cathepsin B." (PMID 37747236, 2023). "Moreover, a limited number of in vivo studies exist that demonstrate that cathepsin L inhibition can prevent infection and limit SARS-CoV-2 pathogenesis." (PMID 36985290, 2023). "During infection, the S protein needs to be cleaved to proteolytic activation by the host cell proteases such as CTSL, which changes the conformation of the S protein from the pre-fusion state to the post-fusion state and eventually favors membrane fusion and genome release." (PMID 37632009, 2023). "Activation of VSV-SARS-CoV-2-Atto 565 by brief treatment with trypsin for 30 minutes followed by the addition of the trypsin inhibitor aprotinin bypassed the requirement for host cell proteases TMPRSS2 and cathepsin L for infection--implicating that trypsin treatment cleaved the S2’ site." (PMID 35951767, 2022). "We found that the depletion of CTSL completely aborted the infection of pseudotyped SARS-CoV-2 S/HIV-1 viruses in CTSL+/TMPRSS2– HEK293T-hACE2high cells, whereas the depletion of TMPRSS2 did not abort the infection of pseudotyped SARS-CoV-2 S/HIV-1 viruses in the same cell line." (PMID 35572668, 2022). "Cathepsin L activity is required for infection by Ebolavirus and VSV-EBO GP (GFP)." (PMID 35320319, 2022). "Furthermore, for the FM-mutants PsVs, overexpression or knockdown of the CTSL gene also significantly affected the infection levels in a dose-dependent manner, similar to the effects on WT PsV." (PMID 35668062, 2022). "Furthermore, CTSL-specific inhibitors not only blocked the infection of PsV/live virus in cells but also reduced the infection rate of live virus significantly ex vivo and in vivo." (PMID 35668062, 2022). "E64D inhibits cathepsin L and prevents the infection of progeny viruses." (PMID 35176124, 2022). "However, the depletion of CTSL in CTSL–/TMPRSS2+ Calu-3 cells only slightly decreased the infection of pseudotyped SARS-CoV-2 S/HIV-1 viruses." (PMID 35572668, 2022). "Both furin and cathepsin L prime SAR-CoV-2 for cell infection." (PMID 33922918, 2021). "In addition, expression of exogenous cathepsin L substantially enhanced infection mediated by the SARS-CoV S protein and by filovirus GP proteins but not by the HCoV-NL63 S protein or the vesicular stomatitis virus G protein." (PMID 34239932, 2021). "However, TMPRSS2 played a more predominant role in virus replication and infection than cathepsin L in primary cells and animal models." (PMID 33420022, 2021). "Cathepsin L in type 0 had a significant increase at 15 dpe and onwards in the infection." (PMID 35071050, 2021). "Similarly, the Furin and TMPRSS2 inhibitors showed no obvious inhibition on the two pangolin coronaviruses, while the Cathepsin L inhibitor had an obvious inhibitory effect on the infection of 293T-hACE2 cells with PCoV-GD and PCoV-GX." (PMID 33824288, 2021).